PTGER2 (prostaglandin E receptor 2)
Diseases named in the same sentence as PTGER2 in open-access papers (continued):
Sharing a sentence is not in itself a finding about the gene and the disease.
polyposis (1 paper, 2018). "Histone acetylation and/or methylation in (myo-) fibroblasts were also demonstrated to regulate expression of the loci involved in the pathogenesis of nasal chronic rhinosinusitis and polyposis, such as prostaglandin E receptor 2 (EP2) gene (PTGER2)." (PMID 29796022, 2018).
prostate carcinoma (1 paper, 2010). A carcinoma that arises from epithelial cells of the prostate gland.
Ureteral obstruction (1 paper, 2012). Obstruction of the flow of urine through the ureter. "Prostaglandins play an important role in ureteral obstruction, but the detailed expression profiles of the prostaglandin receptors (PTGER1, PTGER2, PTGER3, PTGER4, PTGFR) remain unknown in the different parts of the human ureter." (PMID 23227994, 2012).
tumor (16 papers, 2011 to 2024). "generated prostaglandin E receptor-2 (PTGER2) human-specific primers to detect contaminating mouse DNA in multiple tumor types." (PMID 33575432, 2021). "The tumor cell content in the lungs was determined by real-time qPCR analysis to detect human PTGER2 genomic DNA." (PMID 34809669, 2021). "To validate these data further, we analyzed public databases for the association of the expression of “IL-6, PTGER2, and PTGER4” with aggressive tumor phenotypes." (PMID 31014367, 2019). "The use of alternative Cre-driver lines more selective to NK cells as well as a Ptger2 conditional, instead of a germline mutant, allele would be of interest to further explore the cellular targets of PGE2 and their contribution to tumor inflammation and progression." (PMID 33220234, 2020). "Real-time qPCR analysis was performed of human PTGER2 genomic DNA using 1 μg of total DNA as a template to determine the tumor cell content in the lungs, and then the amounts of human genomic DNA initially present in the qPCR reaction tube were extrapolated from the standard curve." (PMID 29416649, 2018). "PTGER2 showed consistent downregulation in both normal and tumor tissue." (PMID 26207152, 2015). "Tumor molecular profiles showed few associations with clinicopathological variables, and these included downregulation of PTGDR and PTGS1 in older patients, overexpression of PTGER2, and hypermethylation of PTGS2 in right side tumors as compared with left colon." (PMID 26207152, 2015). "The receptors PTGER2, PTGER3, and PTGER4 exhibited reduced gene expression in all tumor cells, indicating a reduction in the action of PGE2 on these receptors." (PMID 36678600, 2023). "Intriguingly, scRNA-seq analysis indicates that the expression of EP2 (PTGER2) and EP4 (PTGER4) is negatively correlated with patient prognosis in different tumor types (LUSC, BRCA, LIHC, and OV)." (PMID 38022587, 2023). "In non-tumor cells (HaCaT), the effect was inverse, with an upregulation of PTGS2 and its receptors (PTGER2, PTGER3, and PTGR4), indicating the pro-inflammatory effect of piperine on non-tumor cells." (PMID 36678600, 2023). "A major target of their products seem to be TAMs, which express considerable higher levels of the PGE2 and PGI2 receptor genes PTGER2, PTGER4, and PTGIR with the exception of PTGER3 expressed only by a small subset of tumor cells." (PMID 27215396, 2016). "This is concordant with PGE2 being the major prostanoid in tumor microenvironments and fits previous observations in ApcMin transgenic mice, where deletion of PTGER1, PTGER2, and PTGER4 inhibits the development of CRC." (PMID 26207152, 2015). "Notably, we found that syntenin-1 promoted tumour cell chemosensitivity to L-OHP, presence of CSCs and migration through the regulation of PTGER2 expression." (PMID 32595209, 2020).
cancer (10 papers, 2013 to 2025). A tumor composed of atypical neoplastic, often pleomorphic cells that invade other tissues. "However, the PI3K/AKT signaling pathway was also linked to the PTGER2/PTGER4-triggered COX-2 transcriptional induction after PGE2 stimulation of cancer cells." (PMID 36010605, 2022). "The expression of PTGER2 affects the biologic behavior of various types of malignant tumors, which should be related to the enrichment of pathways in cancer in KEGG analysis." (PMID 34886911, 2021). "Recently, Baba and colleagues found that G protein-coupled receptor PTGER2 overexpression, the downstream target of PGE2, which is involved in inflammation and cancer, is strongly associated with MSI." (PMID 23965959, 2013). "The expression levels of genes involved in cancer invasiveness (MYC, VEGFB, IL33, PTGS2, and PTGER2) were increased." (PMID 37601099, 2023).
infection (3 papers, 2015 to 2022). The state of being infected such as from the introduction of a foreign agent such as serum, vaccine, antigenic substance or organism. "In the hearts of C57BL/6 mice, infection caused a greater significant increase in the expression of Ptger2, which validates the use of EP-2-/- mice in the C57BL/6 background." (PMID 26305786, 2015). "Since the effector function of PGE2 produced by myeloid cells depends on its binding to EP receptors, we studied gene expression of its 4 receptors, EP-1 (Ptger1), EP-2 (Ptger2), EP-3 (Ptger3) and EP-4 (Ptger4), in hearts of mice during infection." (PMID 26305786, 2015). "PTGER2 was significantly upregulated in both CD4+ (p=0.0039) and CD8+ (p=0.0086) T cells in active infection, as were CD4+ TNF expression (p=0.0364) and CD4+ EGR2 expression (p=0.0069)." (PMID 36439147, 2022). "Only two genes (PTGER2 and CD27) were significantly upregulated in active infection, while the remaining five were downregulated." (PMID 36439147, 2022). "Similar to the observations in N67 infection, IL10R, SOCS1, TRIM24, and PTGER2 were also inhibited in mice day 1 infected with 17XNL." (PMID 30327482, 2018).
kidney diseases (1 paper, 2025). "The question about whether PTGER2 plays a protective or detrimental role in kidney diseases lacks general consensus and calls for more investigation." (PMID 40290492, 2025).
PTGER2 also shares sentences with these, for which no sentence is quoted: glioma (3 papers); pulmonary arterial hypertension (2); allergic asthma (1); Allergy (1); autosomal dominant polycystic kidney disease (1); brain tumor (1); bronchiectasis (1); calcification (1); Co-infection (1); cyst (1); duodenitis (1); epilepsy (1); esophageal ulcer (1); gastric cancer (1); gastritis (1); non-small cell lung carcinoma (1); ocular hypertension (1); pulmonary hypertension (1); rectal cancer (1); respiratory allergy (1); Stroke (1); uterine tumor (1).